RNU6-745P (RNA, U6 small nuclear 745, pseudogene)
Gene: Small nuclear RNA gene on chromosome 15 (70,193,236 to 70,193,341, forward strand). Ensembl gene ENSG00000200216.
Homologues: Orthologues: chimpanzee U6 (100% identical), macaque U6 (89% identical), mouse Gm23096 (84% identical), guinea pig U6 (79% identical), guinea pig U6 (76% identical). Paralogues in human: RNU6-774P (88% identical), RNU6-1011P (87% identical), RNU6-12P (87% identical), RNU6-13P (87% identical), RNU6-24P (87% identical), RNU6-32P (87% identical), RNU6-33P (87% identical), RNU6-727P (87% identical), RNU6-842P (87% identical), RNU6-1 (86% identical), RNU6-1029P (86% identical), RNU6-11P (86% identical), and 1285 more.